CDC42BPG (CDC42 binding protein kinase gamma)
Description:
May act as a downstream effector of CDC42 in cytoskeletal reorganization. Contributes to the actomyosin contractility required for cell invasion, through the regulation of MYPT1 and thus MLC2 phosphorylation (By similarity).
Synonyms: MRCKG; DMPK2; HSMDPKIN; MRCKgamma; kappa-200
Tractability: Small molecule: a high-quality ligand is known; it belongs to a druggable protein family. PROTAC: ubiquitination databases record sites on it; a small molecule that binds it is known.
Target class: Kinase; Protein Kinase; AGC protein kinase DMPK family; AGC protein kinase GEK subfamily; AGC protein kinase group; Enzyme
Gene: Protein-coding gene on chromosome 11 (64,823,051 to 64,844,679, reverse strand). Ensembl gene ENSG00000171219.
Subcellular location: Cytoplasm
Subcellular location (Human Protein Atlas): Cytosol
Gene Ontology:
Molecular function: ATP binding; magnesium ion binding; protein binding; protein serine kinase activity; protein serine/threonine kinase activity; protein kinase activity
Biological process: protein phosphorylation; actin cytoskeleton organization; actomyosin structure organization
Cellular component: cell leading edge; cytoplasm; cytosol; cytoskeleton
Genetic constraint (gnomAD): Loss-of-function variants: 150 observed, 165.36 expected, observed/expected ratio (o/e) 0.91, 90% interval 0.79 to 1.04. The upper end of that interval is the gene's LOEUF score, 1.04, which puts it in group 4 of 6, group 1 being the genes least tolerant of losing a copy. Missense variants: 1,963 observed, 1,969 expected, observed/expected ratio (o/e) 1, 90% interval 0.96 to 1.03. Synonymous variants: 968 observed, 845.64 expected, observed/expected ratio (o/e) 1.14, 90% interval 1.09 to 1.21.
Homologues: Orthologues: chimpanzee CDC42BPG (99% identical), macaque CDC42BPG (97% identical), pig CDC42BPG (89% identical), dog CDC42BPG (87% identical), guinea pig CDC42BPG (86% identical), mouse Cdc42bpg (85% identical), rat Cdc42bpg (85% identical), Drosophila melanogaster gek (37% identical), Caenorhabditis elegans mrck-1 (35% identical). Paralogues in human: CDC42BPA (48% identical), CDC42BPB (46% identical), CIT (24% identical), ROCK2 (19% identical), ROCK1 (19% identical).
Diseases named in the same sentence as CDC42BPG in open-access papers:
CDC42BPG is named in the same sentence as 20 diseases in open-access papers, as found by Europe PMC text mining. Sharing a sentence is not in itself a finding about the gene and the disease. The quoted sentences say what the papers report.
gout (4 papers, 2017 to 2023). A condition characterized by painful swelling of the joints, which is caused by deposition of urate crystals. "Because URAT1 is a well-known urate transporter that markedly affects SUA level, these findings indicate that the true associated gene for combined type gout on chromosome 11q13.1 locus is not CDC42BPG, but SLC22A12/URAT1." (PMID 32238385, 2020). "The SNPs rs55975541 in CDC42BPG, and rs11231825/rs9734313 in SLC22A12/NRXN2, and rs10897526 in MAP4K2 on chromosome 4 were previously reported to be associated with hyperuricemia or gout." (PMID 29558500, 2018). "Among these genes, SLC22A12, CDC42BPG, and SLC2A9 were previously found to be related to serum uric acid levels or gout." (PMID 28410202, 2017).
hyperuricemia (4 papers, 2017 to 2020). An abnormally high level of uric acid. "Our findings indicate that CDC42BPG may be a novel susceptibility locus for hyperuricemia." (PMID 29124443, 2018). "Of these SNVs, nine are located at seven gene loci (DDX39B, NFKBIL1, CDC42BPG, CDC63, BRAP, ACAD10, and PCNX3) that might be novel susceptibility loci for hyperuricemia." (PMID 29124443, 2018).
Aarskog syndrome (1 paper, 2024). "rs55975541 in CDC42BPG, a variant with damaging PolyPhen and SIFT predictions, was found to be enriched; CDC42BPG is downstream of CDC42, the direct downstream target of the causative gene of Aarskog syndrome, FGD1." (PMID 38785976, 2024).
osteosarcoma (1 paper, 2017). A usually aggressive malignant bone-forming mesenchymal neoplasm, predominantly affecting adolescents and young adults. "Moreover, ectopic expression of CDC42BPG, FST344 (major isoform of FST) or FST311 (minor isoform of FST) reduced cell proliferation, which indicated that these genes also had growth suppressive effects in osteosarcoma cell lines." (PMID 28878391, 2017).
CDC42BPG also shares sentences with these, for which no sentence is quoted: autism spectrum disorder (2 papers); Alzheimer disease (1); amyotrophic lateral sclerosis (1); bipolar disorder (1); cervical cancer (1); depression (1); diabetic retinopathy (1); epilepsy (1); Intellectual disability (1); lung adenocarcinoma (1); lung carcinoma (1); lung squamous cell carcinoma (1); myotonic dystrophy (1); Parkinson disease (1); Pituitary adenoma (1); tumour (1).